C2orf72 ( chromosome 2 open reading frame 72 )
Synonyms: LOC257407
Tractability: Antibody: the Human Protein Atlas places it where antibodies can reach. PROTAC: its protein half-life has been measured.
Gene: Protein-coding gene on chromosome 2 (231,037,342 to 231,049,719, forward strand). Ensembl gene ENSG00000204128.
Subcellular location (Human Protein Atlas): Nucleoplasm; Plasma membrane
Genetic constraint (gnomAD): Loss-of-function variants: 15 observed, 8.52 expected, observed/expected ratio (o/e) 1.76, 90% interval 1.11 to 1.96. That is too few expected variants to judge how well the gene tolerates losing a copy. Missense variants: 347 observed, 278.36 expected, observed/expected ratio (o/e) 1.25, 90% interval 1.14 to 1.36. Synonymous variants: 159 observed, 130.03 expected, observed/expected ratio (o/e) 1.22, 90% interval 1.07 to 1.39.
Homologues: Orthologues: chimpanzee C2orf72 (95% identical), macaque C12H2orf72 (83% identical), pig C2orf72 (75% identical), dog C2orf72 (71% identical), rat C9h2orf72 (71% identical), mouse 2810459M11Rik (69% identical).